NCK2 (NCK adaptor protein 2)
Description:
Adapter protein which associates with tyrosine-phosphorylated growth factor receptors or their cellular substrates. Maintains low levels of EIF2S1 phosphorylation by promoting its dephosphorylation by PP1. Plays a role in ELK1-dependent transcriptional activation in response to activated Ras signaling.
Synonyms: GRB4; NCKbeta
Tractability: Small molecule: a structure with a bound ligand is known. PROTAC: its protein half-life has been measured.
Gene: Protein-coding gene on chromosome 2 (105,744,369 to 105,894,275, forward strand). Ensembl gene ENSG00000071051.
Subcellular location: Cytoplasm; Endoplasmic reticulum
Pathways (Reactome):
Signal Transduction: Downstream signal transduction; RHOU GTPase cycle; RHOV GTPase cycle; VEGFA-VEGFR2 Pathway
Developmental Biology: Activation of RAC1; Ephrin signaling; Regulation of cortical dendrite branching
Cell-Cell communication: Nephrin family interactions
Gene Ontology:
Molecular function: phosphotyrosine residue binding; protein binding; cytoskeletal anchor activity; receptor tyrosine kinase binding; signaling adaptor activity; signaling receptor complex adaptor activity; protein-containing complex binding; scaffold protein binding
Biological process: positive regulation of actin filament polymerization; positive regulation of T cell proliferation; positive regulation of transcription by RNA polymerase II; cell migration; ephrin receptor signaling pathway; epidermal growth factor receptor signaling pathway; negative regulation of cell population proliferation; negative regulation of PERK-mediated unfolded protein response; positive regulation of endoplasmic reticulum stress-induced intrinsic apoptotic signaling pathway; positive regulation of translation in response to endoplasmic reticulum stress; signal complex assembly; signal transduction; T cell activation; negative regulation of transcription by RNA polymerase II; regulation of transcription by RNA polymerase II; regulation of translation initiation in response to endoplasmic reticulum stress; response to endoplasmic reticulum stress
Cellular component: cytoplasm; endoplasmic reticulum; cytosol; postsynaptic density; synapse; vesicle membrane
Genetic constraint (gnomAD): Loss-of-function variants: 16 observed, 33.22 expected, observed/expected ratio (o/e) 0.48, 90% interval 0.32 to 0.73. The upper end of that interval is the gene's LOEUF score, 0.73, which puts it in group 2 of 6, group 1 being the genes least tolerant of losing a copy. Missense variants: 418 observed, 533.41 expected, observed/expected ratio (o/e) 0.78, 90% interval 0.72 to 0.85. Synonymous variants: 273 observed, 244.68 expected, observed/expected ratio (o/e) 1.12, 90% interval 1.01 to 1.23.
Homologues: Orthologues: chimpanzee NCK2 (100% identical), macaque NCK2 (99% identical), dog NCK2 (98% identical), rabbit NCK2 (98% identical), mouse Nck2 (96% identical), rat Nck2 (96% identical), pig NCK2 (89% identical), guinea pig NCK2 (88% identical), tropical clawed frog nck2 (84% identical), zebrafish nck2a (81% identical), zebrafish nck2b (81% identical), Drosophila melanogaster dock (45% identical), and 1 more. Paralogues in human: NCK1 (68% identical), GRAP (17% identical), GRAP2 (16% identical), GRB2 (16% identical), GRAPL (12% identical), SLA (12% identical), SLA2 (12% identical), DAPP1 (12% identical), SH2D5 (11% identical).
Diseases named in the same sentence as NCK2 in open-access papers:
NCK2 is named in the same sentence as 32 diseases in open-access papers, as found by Europe PMC text mining. Sharing a sentence is not in itself a finding about the gene and the disease. The quoted sentences say what the papers report.
breast carcinoma (5 papers, 2009 to 2023). "Further investigation is needed to understand the mechanisms by which NCK1 and NCK2 signalling in development may be abnormally activated in breast cancer." (PMID 37479911, 2023). "Notably, during the course of this investigation, NCK1 and NCK2 were identified as drivers of breast cancer progression and metastasis." (PMID 37479911, 2023). "To find out whether increased expression of Nck2 during cancer progression is observed in other cancer types than in melanoma skin cancer, we assessed Nck isoforms protein levels in murine colon (CT) and human breast cancer cell lines at different stages of progression." (PMID 21992144, 2011). "In contrast, Nck2 was only detected in the most aggressive MDA-MB-231 cells, which are mesenchymal-like ER+ breast cancer cells with strong migratory and metastatic abilities." (PMID 21992144, 2011). "We found that the vast majority of IGF regulators were upregulated in various cancers, such as HRAS and YWHAZ in lung squamous cell carcinoma (LUSC), SHC1 in kidney cancer, PRKCZ in bladder cancer (BLCA) and in breast cancer (BRCA), and NCK2 in cholangiocarcinoma (CHOL)." (PMID 35935986, 2022). "We show that a decrease in adaptor protein Nck1, but not Nck2, is necessary for cell killing in both ER positive and ER negative breast cancer cell lines." (PMID 23706161, 2013).
melanoma (5 papers, 2011 to 2025). A malignant, usually aggressive tumor composed of atypical, neoplastic melanocytes. "Consistent with our results, NCK2 promotes the proliferation of human primary melanoma by modulating phosphatase activities." (PMID 37292517, 2023). "Altogether, these results suggest that Nck2 promotes cell migration and invasion in human melanoma cells." (PMID 21992144, 2011). "To investigate the mechanism by which Nck2 overexpression impinges on the phenotype of primary melanoma cells, we compared the levels of tyrosine phosphorylated proteins between human melanoma cells expressing different levels of Nck2 protein." (PMID 21992144, 2011). "More importantly, we found that cell proliferation was significantly decreased in Nck2 depleted metastatic melanoma cells compared with control siRNA treated cells." (PMID 21992144, 2011). "Nck2 siRNA transfection of 451Lu metastatic melanoma cells resulted in decreased Nck2 protein and mRNA levels, while Nck1 protein and mRNA levels were not altered." (PMID 21992144, 2011). "Increasing levels of GFP-Nck2 in WM278 melanoma cells promoted migration and this was significant in cell line N14, which expresses higher levels of Nck2 proteins compared with N5 and N7 cell lines." (PMID 21992144, 2011). "Nevertheless, in line with our in vitro studies, these results strongly support a role for Nck2 in melanoma-derived tumor growth rate in vivo." (PMID 21992144, 2011). "Collectively, our data indicate that Nck2 effectively influences human melanoma phenotype progression." (PMID 21992144, 2011). "Collectively, our data support Nck2 as a cornerstone governing the aspects that promote melanoma progression." (PMID 21992144, 2011). "It is interesting to note though that the effect of Nck2 on WM278 primary melanoma cells proliferation seems to parallel the levels of Nck2 overexpressed (compared N15, N7 and N14)." (PMID 21992144, 2011). "In agreement, we found that Nck2 overexpression significantly promoted primary melanoma cells invasion through MatrigelTM matrix in transwells assays." (PMID 21992144, 2011). "We demonstrated the involvement of Nck2 in proliferation, migration and invasion in human melanoma cells." (PMID 21992144, 2011). "In conclusion, in this study we provide evidence for a role of the adaptor protein Nck2 in melanoma proliferation, migration and invasion in vitro and melanoma-derived tumor growth in vivo." (PMID 21992144, 2011). "Altogether, these results indicate that Nck2 contributes to the control of proliferation in human melanoma cells." (PMID 21992144, 2011). "Additional comparison of highly metastatic (WM1617) and weakly metastatic (WM278) human melanoma cell lines isolated from the same patient, further confirmed increased expression of Nck2 in human metastatic melanoma." (PMID 21992144, 2011). "In contrast, we observed a strong increase in Nck2 mRNA levels in all human melanoma cell lines compared with HEM." (PMID 21992144, 2011). "Our investigation revealing that Nck2 overexpression in human primary melanoma cells induces metastatic characteristics point towards Nck2 sufficiency to promote metastasis phenotype." (PMID 21992144, 2011). "Further analyses using in-house generated Nck isoforms specific antibodies revealed that increased expression of Nck in metastatic melanoma cells is mainly due to drastic higher expression levels of Nck2 (compare WM164 and 451Lu with WM278)." (PMID 21992144, 2011). "Furthermore, in another investigation Nck2 protein and mRNA levels were increased in human metastatic melanoma cells compared with human primary melanoma cells that rarely metastasized." (PMID 29088810, 2017). "Genetic variants of rs6707820 C>T in NCK2 and rs2306574 T>C in PRKCD of the PDGF signaling pathway may be biomarkers for melanoma survival." (PMID 29088810, 2017).
melanoma (continued). "To determine whether overexpression of Nck2 in primary melanoma cells promotes invasion in a tumor-like context, we evaluated migration of melanoma cells at the edge of multicellular spheroids embedded into a collagen type I matrix." (PMID 21992144, 2011). "Collectively, our findings indicate that Nck2 plays a role in human melanoma progression." (PMID 21992144, 2011). "Finally, in mice we assessed tumor growth rate of human melanoma cells expressing increasing levels of Nck2." (PMID 21992144, 2011). "Importantly, we uncovered that injection of Nck2-overexpressing human primary melanoma cells into mice increases melanoma-derived tumor growth rate." (PMID 21992144, 2011). "None the less, our findings clearly demonstrate that overexpression of Nck2 in human primary melanoma correlates with upregulation of the total phospho-tyrosine proteins content, assembly of novel Nck2-dependent pY-protein complexes and downregulation of E- and N-cadherins, and β-1 and -3 integrins." (PMID 21992144, 2011). "To establish the biological relevance of our findings, we examined whether overexpression of Nck2 in human primary melanoma cells confers some tumorigenic advantage in a xenograft mouse model." (PMID 21992144, 2011). "In addition, we found that tyrosine phosphorylated proteins coimmunoprecipitated with Nck2 (Nck2 IP) or total Nck (pan-Nck IP) were more abundant in human metastatic melanoma WM1617 cells compared with the counterpart WM278 primary melanoma cells." (PMID 21992144, 2011). "Collectively, these results reveal that increased expression of Nck2 in human primary melanoma cells promotes phosphorylation of proteins on tyrosine, concomitant with the assembly of Nck2-dependent pY-proteins containing molecular complexes and downregulation of cell surface adhesion proteins." (PMID 21992144, 2011). "To confirm a role for Nck2 in melanoma cell proliferation, we assessed whether siRNA-mediated downregulation of Nck2 in human metastatic melanoma cells affects cell proliferation." (PMID 21992144, 2011). "Altogether, these results suggest a specific role for Nck2 in human melanoma progression." (PMID 21992144, 2011). "This does not exclude that other yet identified players could be required to fully promote metastasis in melanoma overexpressing Nck2." (PMID 21992144, 2011). "In addition, using an in vivo xenograft model, we provide evidence that increased Nck2 expression in human primary melanoma cells promotes melanoma-derived tumor growth rate." (PMID 21992144, 2011). "In contrast, vinculin staining, which shows that GFP-Nck2 colocalizes with vinculin at focal adhesions, revealed significant reduced number of focal adhesions in human primary melanoma cells overexpressing Nck2 (N14) compared with control melanoma cells (C2)." (PMID 21992144, 2011). "We show that Nck2 promotes cell proliferation, migration and invasion in human melanoma cells." (PMID 21992144, 2011). "Moreover, we discovered that Nck2 overexpression in human primary melanoma cells correlates with higher levels of proteins phosphorylated on tyrosine residues, assembly of Nck2-dependent pY-proteins-containing molecular complexes and downregulation of cadherins and integrins." (PMID 21992144, 2011). "To demonstrate a role for Nck2 in melanoma progression, we first determined whether Nck2 regulates cell proliferation in WM278 human primary melanoma cells, which endogenously express low levels of Nck2 protein and rarely metastasis compared with its metastatic counterpart WM1617 melanoma cells." (PMID 21992144, 2011). "In this study, we provide evidence that Nck2 plays a role in promoting proliferation, migration and invasion of human melanoma cells in vitro and growth of melanoma-derived tumors in vivo, while its expression is upregulated in metastatic cancer cells, including colon, breast and melanoma." (PMID 21992144, 2011).
melanoma (continued). "Therefore, increased expression of Nck2 in human primary melanoma cells may elicit protein interactions that re-wire signaling pathways in a fashion that alters focal adhesions and promotes cell motility by interacting with FAK and PINCH." (PMID 21992144, 2011). "However, our results demonstrate that increased endogenous expression of Nck2 in human metastatic melanoma cells relative to primary melanoma cells and melanocytes results from increased Nck2 transcription, suggesting that Nck1 and Nck2 promoters are under different regulatory controls." (PMID 21992144, 2011). "Therefore, we next determined whether Nck2 was critical to melanoma cell migration and invasion." (PMID 21992144, 2011). "In agreement, the WM1617 human metastatic melanoma cells that endogenously express higher levels of Nck2 compared with human primary melanoma cells, also show higher proliferative abilities than its paired WM278 primary melanoma cells that rarely metastasis." (PMID 21992144, 2011). "This suggests that overexpression of Nck2 has no major effect on actin polymerization and organization, as well as on overall cell morphology in human primary melanoma." (PMID 21992144, 2011). "By western blot analysis, we compared levels of proteins phosphorylated on tyrosine as well as cadherins and integrins in human melanoma cells overexpressing or not Nck2." (PMID 21992144, 2011). "Altogether, these observations suggest that increased expression of Nck2 in human melanoma cells is not sufficient to promote the appearance of subcutaneous tumor derived from melanoma." (PMID 21992144, 2011). "In addition, compared with primary melanoma cells (WM278), metastatic melanoma cell lines (WM164 and 451LU) showed significant increased Nck2 mRNA levels." (PMID 21992144, 2011). "NCK2 can modulate cell motility by interacting with focal adhesion through its SH3/SH2 domain and may influence tumor aggressiveness by mediating cell–extracellular matrix interactions in ovarian cancer and promote melanoma progression in vitro and in vivo." (PMID 34290732, 2021). "In this study, we did not address whether Nck2 is necessary for melanoma metastasis." (PMID 21992144, 2011).
atherosclerosis (2 papers, 2022 to 2024). A disease characterized by the build-up of fatty material and calcium deposition in the arterial wall resulting in partial or complete occlusion of the arterial lumen. "Male and female Nck1-null atheroprone mice enabling inducible, endothelial-specific Nck2 inactivation were fed a high fat diet (HFD) for 8 or 16 weeks to model atherosclerosis initiation and progression, respectively." (PMID 36035930, 2022). "Analysis of the data in this fashion highlights the sex-specific effects of endothelial NCK2 in atherosclerosis." (PMID 36035930, 2022). "Taken together, endothelial NCK2 signaling promotes a plaque phenotype with increased smooth muscle cell contribution during atherosclerosis progression in females." (PMID 36035930, 2022). "Collectively, our results demonstrate stage- and sex-dependent modulation of atherosclerosis development by endothelial NCK2 signaling." (PMID 36035930, 2022). "Here, we report stage- and sex-dependent effects of endothelial NCK2 signaling on arterial wall inflammation and atherosclerosis development." (PMID 36035930, 2022). "Given the non‐redundant roles of NCK1 and NCK2 in inflammation and atherosclerosis, we hypothesized that NCK1 might play an important role in platelet activation and thrombosis." (PMID 38922767, 2024). "During atherosclerosis progression, however, abrogation of endothelial NCK2 signaling ameliorates inflammation of the arterial wall in both sexes, whereas severity of lesions and atherosclerosis progression are reduced in male, but not female, Nck1-null atheroprone mice." (PMID 36035930, 2022). "Markers of vascular inflammation were reduced by endothelial NCK2 deficiency in both males and females during atherosclerosis progression but not initiation." (PMID 36035930, 2022). "In the present study, we show that inducible, endothelial-specific deletion of NCK2 does not impact HFD-induced atherosclerosis initiation." (PMID 36035930, 2022). "In sum, endothelial NCK2 signaling promotes atherosclerosis progression, but not initiation, through a mechanism that involves increased expression of ICAM-1 in the arterial wall and neointimal/intimal layers." (PMID 36035930, 2022).
metastatic melanoma (2 papers, 2011 to 2017). A melanoma that has spread from its primary site to another anatomic site. "In addition, we demonstrate that depletion of Nck2 in metastatic melanoma reduces cell proliferation." (PMID 21992144, 2011). "Particularly, we observed significant higher levels of Nck2 protein and mRNA, as opposed to no change in Nck1, in human metastatic melanoma cell lines compared with non-metastatic melanoma and normal melanocytes." (PMID 21992144, 2011). "Most recently, the Nck2 gene was found as being overexpressed in human metastatic melanoma compared with non-metastatic melanoma lesions." (PMID 21992144, 2011).
opiate dependence (2 papers, 2012 to 2013). Disorders related or resulting from abuse or mis-use of opioids. "In our analysis, we find a genome-wide significant association of NCK2 gene on chromosome 2 with opiates dependence in African-origin men at both the SNP and gene levels." (PMID 23533358, 2013). "Therefore, both methods provided significant evidence that supports the association between the NCK2 gene and opiates dependence in African-origin men." (PMID 23533358, 2013). "The NCK2 gene that contains SNP rs2377339 also achieved the genome-wide significance for opiates dependence at the gene level." (PMID 23533358, 2013).
ovarian carcinoma (2 papers, 2021 to 2023). A malignant neoplasm originating from the surface ovarian epithelium. "Additionally, NCK2 can be a significant contributor in enhancing tumor survival and aggressiveness in ovarian cancer." (PMID 36761433, 2023).
substance dependence (2 papers, 2012 to 2013). The psychological or physiological need to take a substance in order to experience its effects or to avoid the effects of its absence. "Codependence analysis also identified a genome-wide significant association between NCK2 and comorbidity of substance dependence (P value = 3.65E − 08) in African-origin men." (PMID 23533358, 2013). "This approach, which is a realistic depiction of substance dependence, confirmed that a novel susceptibility gene, NCK2 is significantly associated with substance dependence in African-origin men." (PMID 23533358, 2013). "Another gene, NCK2, is nearly genome-wide significant (P = 2.7E − 6) in its association with substance dependence." (PMID 23365539, 2012).
Alzheimer disease (1 paper, 2021). A progressive, neurodegenerative disease characterized by loss of function and death of nerve cells in several areas of the brain leading to loss of cognitive function such as memory and language. "The Nck2 gene localizes to chromosome 2 band q12 (2q12) in a region linked to neurological development, and GWAS analysis link Nck2 SNPs to drug addiction, Alzheimer’s Disease, and platelet levels." (PMID 34124074, 2021).